CTLA4 (cytotoxic T-lymphocyte associated protein 4)
Diseases named in the same sentence as CTLA4 in open-access papers (continued):
Sharing a sentence is not in itself a finding about the gene and the disease.
melanoma (continued). "In slightly earlier ICI studies, the role of CTLA-4 (cytotoxic T-lymphocyte associated protein-4)-directed monoclonal antibodies was explored following the success of ipilimumab against melanoma in 2011." (PMID 37173972, 2023). "In our models, the low-risk-group patients with melanoma enriched higher expression of PD-1/PD-L1 and CTLA4, and showed promising responses to anti-PD-1 therapy." (PMID 37217516, 2023). "A 54-year-old man with melanoma developed personality changes and memory loss after four cycles of treatment with the CTLA-4 inhibitor ipilimumab." (PMID 37240574, 2023). "So, four types of IPS values, including PD-1-positive score or CTLA4-positive, were used to explore the prediction for the immunotherapeutic outcome of melanoma patients in high- and low-risk groups." (PMID 37217516, 2023). "They discovered that mouse melanoma and breast tumors were significantly more sensitive to anti-CTLA4 and/or anti-PD1 ICB when there was a deficiency in the expression of BIRC2." (PMID 37781078, 2023). "This study sought to evaluate GSL incidence in patients with high-risk melanoma treated with cytotoxic T-lymphocyte antigen 4 (CTLA4) or programmed cell death 1 (PD1) blockade adjuvant therapy in two clinical trials: ECOG-ACRIN E1609 and SWOG S1404." (PMID 37174027, 2023). "This study examined GSL incidence in patients with high-risk melanoma treated with CTLA4 or PD1 blocking adjuvant therapy in two randomized clinical trials, the ECOG-ACRIN E1609 and SWOG S1404." (PMID 37174027, 2023). "Anti‐CTLA‐4 monotherapy was associated with longer OS for patients with melanoma, whereas anti‐PD‐L1 + anti‐CLTA‐4 combination therapy were associated with longer OS for NSCLC and RCC." (PMID 37962239, 2023). "The first of these, ipilimumab, blocks cytotoxic T-lymphocyte-associated antigen 4 (CTLA-4) and was approved to treat advanced melanoma in 2011." (PMID 37627204, 2023). "Recent studies suggest that BRAFV600-mutated melanomas in particular respond to dual anti-programmed cell death protein 1 (PD-1) and anti-cytotoxic T lymphocyte-associated protein 4 (CTLA-4) immune checkpoint inhibition (ICI)." (PMID 37525015, 2023). "Immune checkpoint molecules (such as PDCD1, CD274, and CTLA4) and co-stimulatory molecules were also highly expressed in low-risk melanoma group (FDR-adjusted P < 0.05, one-sided Wilcoxon rank-sum test)." (PMID 37620409, 2023). "Using the AUS cohort, we observed a decrease in CTLA4 expression in the blood of melanoma patients, and this reduction was associated with a poorer prognosis for patients with metastatic melanoma." (PMID 37197667, 2023). "Ipilimumab was the first FDA-approved antibody in melanoma that inhibits signaling via cytotoxic T-lymphocyte-associated proteins (CTLA-4) on T cells." (PMID 36768822, 2023). "In contrast, prolonged IFN-γ exposure caused resistance to radiotherapy and anti-CTLA-4 treatment in melanoma cells." (PMID 38139110, 2023). "After finding that blood CTLA4 expression was associated with melanoma patients’ OS, we aimed to investigate which specific blood cell subtypes were responsible for the downregulation of CTLA4 expression." (PMID 37197667, 2023). "Neoadjuvant treatment with anti-CTLA4 of advanced melanoma was associated with increased levels of circulating FOXP3-positive Treg cells, which interestingly correlated with a better prognosis." (PMID 37568571, 2023). "Using data from The Cancer Genome Atlas (TCGA) melanoma database and another dataset, we found that decreased CTLA4 mRNA was associated with a poorer prognosis in metastatic melanoma." (PMID 37197667, 2023). "Combined immune checkpoint blockage (ICB) targeting the cytotoxic T lymphocyte–associated protein 4 (CTLA-4) and PD-1, has shown great efficacy in the treatment of metastasized malignant melanoma and renal cell carcinoma." (PMID 37415208, 2023).
melanoma (continued). "The first ICI approved by the Food and Drug Administration (FDA) was the drug ipilimumab (cytotoxic T-lymphocyte associated protein 4 (CTLA-4) inhibitor), which was approved for the treatment of melanoma in 2011." (PMID 37046461, 2023). "Immune checkpoint inhibitors (ICIs), including anti-cytotoxic T-lymphocyte-associated protein 4 (CTLA-4) and anti-programmed death-1 (PD-1) antibodies, have initiated a new era in the treatment of malignant melanoma." (PMID 38139110, 2023). "Programmed cell death protein 1 (PD-1) blockade is effective in the treatment of Hodgkin’s lymphoma (HL), and cytotoxic T lymphocyte associated antigen 4 (CTLA4) immunotherapy has shown significant antitumor effects in melanoma." (PMID 37889551, 2023). "Our results show that increased expression of ITGAL is associated not only with PD1 and CTLA4, but also with other potential melanoma checkpoints (LAG-3, Tim-3, and TIGIT)." (PMID 37388230, 2023). "A study examined the effect of a PD-1 inhibitor on patients with melanoma who had experienced ipilimumab (CTLA-4 inhibitor)-associated immune toxicity and found that most irAEs observed were new rather than recurrent." (PMID 37055838, 2023). "Several ICBs have been approved for melanoma, including the cytotoxic T lymphocyte-associated protein 4 (CTLA-4) antibody ipilimumab and two programmed cell death protein 1 (PD-1) antibodies, nivolumab and pembrolizumab." (PMID 37404751, 2023). "Since anti-cytotoxic T-lymphocyte-associated protein 4 (anti-CTLA4) was approved for advanced melanoma treatment in 2011, ICIs have rapidly gained approval and been used to treat various cancers, which has led to an unprecedented increase in survival." (PMID 37698530, 2023). "High mutation load, defined as > 100 nonsynonymous single-nucleotide variants (nsSNV) per exome, was associated with clinical benefit in melanoma patients treated with anti-CTLA‐4 therapy." (PMID 37420037, 2023). "Similar results were obtained in melanoma patients in whom anti-CTLA-4 efficacy was associated with T cell responses mediated by an overabundance of B. fragilis or Bacteroides thetaiotaomicron." (PMID 38046824, 2023). "In accordance with this, inhibition of SKI has been associated with the enhancement of the effect of anti-CTLA-4 and anti-PD-1 immunotherapies on melanoma cells in vitro." (PMID 35515106, 2022). "In patients on CTLA-4 inhibitors, the cancer type of melanoma was positively associated with the risk of severe cases [B = 3.607, OR 36.873, 95% CI (1.833–741.761), p = 0.018]." (PMID 35870109, 2022). "In advanced melanoma with acquired immunotherapy resistance (such as anti-PD-1 and anti-CTLA-4 mAbs), loss-of function (LOF) mutations are very frequent, especially in such important genes as JAK1/2, IRF1, and IFNGRI1/2." (PMID 35269988, 2022). "For instance, baseline gut microbiota enrichment with Bacteroides was associated with shorter PFS and OS in melanoma patients treated with CTLA-4 inhibitors." (PMID 36358789, 2022). "Immune checkpoint blockade (ICB) is widely used in the treatment of melanomas, especially those with negative regulators, such as T-lymphocyte associated protein-4 (CTLA-4), programmed death receptor 1 (PD-1), and the ligands of PD-1 (PD-L1)." (PMID 35759331, 2022). "An observational study showed that patients with melanoma and high BMI treated with ipilimumab (anti-CTLA-4 antibody) had a greater response and less susceptibility to metastasis to the brain, in addition to having a longer OS." (PMID 36033972, 2022). "In order to validate the predictive value of HRR pathway mutation for the efficacy of anti-CTLA4 therapy in melanoma, it was also performed using a pooled cohort receiving anti-CTLA-4 therapy for the data analysis." (PMID 35990677, 2022). "Correspondingly, co-administration of adenovirus encoding a chimeric, membrane-bound CD40 ligand (ISF35) with PD-1 and CTLA-4 inhibitors caused complete removing of injected tumor cells in the melanoma murine model." (PMID 34980128, 2022).
melanoma (continued). "Recently, ferroptotic induction was reported to be the key factor for tumor regression caused by the blockade of programmed cell death-ligand 1 (PD-L1) plus cytotoxic T-lymphocyte associated antigen 4 (CTLA-4) in melanoma." (PMID 36267413, 2022). "Recently developed therapeutic interventions target melanoma metastasis by blocking immune checkpoints using cytotoxic T-lymphocyte-associated antigen 4 (CTLA-4) or programmed death 1 (PD-1) inhibitors." (PMID 36038818, 2022). "Conversely, a higher YBX3 expression was associated with more benefits of CTLA4 ICB in melanoma patients and thus a prolonged survival period." (PMID 36059530, 2022). "The response rate of anti-PD-1 or anti-CTLA4 immunotherapy in melanoma patients was significantly higher in the low-risk group, while patients in the high-risk group presented a greater sensitivity to chemotherapy." (PMID 35692844, 2022). "More recently, immunotherapies with checkpoint blockade Abs directed against PD-1 and cytotoxic T-lymphocyte-associated antigen 4 (CTLA-4) have revolutionized the treatment of patients with metastatic cancer including melanoma." (PMID 35814399, 2022). "In March 2011, immune checkpoint inhibition was introduced as a new cancer therapeutic paradigm with FDA approval of the anti-cytotoxic T lymphocyte-associated antigen-4(CTLA-4) antibody ipilimumab for the treatment of advanced melanoma." (PMID 35140720, 2022). "Combination approaches of PD-1 and cytotoxic T lymphocyte-associated protein-4 inhibitors, which showed synergistic efficacy in melanoma, were associated with disappointing results in HNSCC." (PMID 36555876, 2022). "A high TMB was first noted to be associated with the treatment response of cytotoxic T-lymphocyte-associated protein 4 (CTLA-4) inhibitors in melanoma." (PMID 35563486, 2022). "For example, in melanoma, clinically actionable checkpoint inhibitors are directed against programmed death 1 (PD-1), cytotoxic T-lymphocyte-associated antigen 4 (CTLA-4), programmed death ligand 1 (PD-L1), and lymphocyte-activation protein 3 (LAG3)." (PMID 36612082, 2022). "Immunotherapy based on cytotoxic T lymphocyte-associated antigen 4 (CTLA4), programmed death-1 (PD-1) and programmed death ligand-1 (PD-L1) inhibitors have emerged as an effective treatment in melanoma, non-small cell lung carcinoma and glioma." (PMID 35741647, 2022). "Although many studies have focused on the association between CPI response and microbiome profile, one recent study linked toxicity with dual CTLA-4 and PD-1 inhibition to an increased abundance of Bacteroides intestinalis in the stool of melanoma patients." (PMID 35228755, 2022). "This is consistent with some previous studies which have shown that high TMB is associated with response to anti-CTLA-4 in melanoma, and anti-PD1 in NSCLC." (PMID 36189296, 2022). "Recently, somatic mutations in SERPINB4 and SERPINB3 (predominantly missense mutations) were described in melanoma, and were associated with improved survival after anti-CTLA4 immunotherapy." (PMID 35085295, 2022). "In patients, high TIGIT/DNAM-1 ratio on tumor-infiltrating Tregs has been found to be associated with poor clinical outcomes in melanoma following anti-PD-1 or anti-CTLA-4 therapies." (PMID 35273608, 2022). "The first approved ICI therapy was ipilimumab, a cytotoxic T-lymphocyte associated protein 4 (CTLA-4) antagonist, in 2011 for melanoma." (PMID 36345032, 2022). "Analysis from the “Gide 2019” cohort revealed that low ACAP1 levels were also associated with inferior response, OS, and PFS in melanoma patients treated with anti-PD-1 alone or in combination with anti-CTLA-4 antibodies." (PMID 36497434, 2022).
melanoma (continued). "It was shown in both pre-clinical studies and in melanoma patients that local RT enhanced systemic responses to anti-cytotoxic T-lymphocyte-associated protein 4 (CTLA4) immunotherapy." (PMID 35804830, 2022). "A study demonstrated that the abundance of Bacteroides intestinalis is correlated with IL-1β production and toxicity caused by the combination of CTLA-4 and PD-1 blockade in patients with melanoma." (PMID 36046819, 2022). "A higher baseline level of soluble CTLA-4 (sCTLA-4) is closely associated with irAEs in patients with melanoma, especially in the gastrointestinal tract." (PMID 36189293, 2022). "Anti-cytotoxic T lymphocyte-associated protein 4 (CTLA-4) was approved in 2011 for the treatment of advanced melanoma, and other immune checkpoint inhibitors (ICIs) were quickly approved by the Food and Drug Administration." (PMID 36091077, 2022). "T cells in high-glycolytic-flux melanoma areas express cytotoxic T lymphocyte-associated protein 4 (CTLA-4)." (PMID 36620597, 2022). "Among targeted therapies used, immunotherapy administration of anti-CTLA-4 antibodies has been described as leading to the uncommon occurrence of pseudoprogression of melanoma, potentially causing new lesions." (PMID 35323369, 2022). "Immune checkpoint inhibitors (ICIs) targeting programmed cell death-1 (PD-1) or cytotoxic T lymphocyte-associated protein-4 (CTLA-4) have achieved tumor regression in several cancers, such as melanoma, lung cancers, and Hodgkin lymphoma." (PMID 35572595, 2022). "Clinical response to anti-CTLA-4 in advanced melanoma is associated with tumor mutational load, and an increase of TILs can be observed as early as three weeks post-treatment." (PMID 35326731, 2022). "In a person with HIV on ART receiving anti-CTLA-4 followed by anti-PD-1 for melanoma, we previously observed a marked increase in cell-associated and plasma HIV RNA, indicative of latency reversal in vivo." (PMID 35123267, 2022). "In this work we analyzed baseline clinical, immune and virological variables as potential predictors of anti-PD-1 & anti-CTLA-4 combination therapy associated ICB-hepatitis in patients with stage III/IV melanoma." (PMID 36503532, 2022). "The hyperactivation of the β-catenin signalling pathway has been linked to elevated expressions of CTLA-4 and IL-10 in human melanomas, thereby establishing an immunosuppressive tumour microenvironment that favours tumour-cell proliferation." (PMID 36068277, 2022). "Immune checkpoint inhibitors (ICI), including the programmed death protein 1 (PD-1, pembrolizumab, nivolumab) and cytotoxic T lymphocyte associated protein 4 (CTLA-4, ipilimumab), recently turned out to be effective in melanoma treatment." (PMID 35006344, 2022). "In phase I clinical trials, T-Vec with ipilimumab (a cytotoxic T lymphocyte-associated antigen 4 [CTLA-4] monoclonal antibody [mAb]) or pembrolizumab (a programmed cell death protein 1 [PD-1] mAb) has shown excellent efficacy in melanoma patients." (PMID 35024377, 2022). "Using subclass mapping, we compared the TCGA expression profiles of the three immune subtypes with another published dataset (GSE91061) from 47 patients with melanoma who received PD-1 inhibitors or cytotoxic T-lymphocyte-associated protein-4 inhibitors." (PMID 36146529, 2022). "The success of anti-cytotoxic T lymphocyte associated antigen 4 (CTLA-4) antibodies in blocking immune checkpoints in advanced melanoma patients offers hope for immunotherapy of tumors." (PMID 35000616, 2022). "A recent study found that gut microbiota signatures are associated with irAEs to CICB targeting CTLA-4 and PD-1 in melanoma patients and in experimental models." (PMID 35432346, 2022). "We previously reported that patients with advanced melanoma harboring loss of IFN-γ signaling genes were resistant to anti-CTLA-4 therapy." (PMID 36008408, 2022).
melanoma (continued). "Therapeutic targeting of immune checkpoints such as programmed death-ligand 1, programmed cell death protein 1 (PD-1) and cytotoxic T-lymphocyte-associated protein 4 (CTLA-4) with ICIs has revolutionized the treatment of advanced melanoma." (PMID 35228751, 2022). "Immune checkpoint inhibitors (ICI), e.g., monoclonal antibodies targeting cytotoxic T-lymphocyte-associated antigen-4 (CTLA-4), programmed cell death protein-1 (PD-1) and PD-ligand 1 (PD-L1), have revolutionized the treatment of advanced melanoma." (PMID 36291928, 2022). "Conversely, they found better OS in melanoma anti‐CTLA4 recipients harbouring an HLA‐B44 supertype allele." (PMID 35394069, 2022). "For instance, metformin can exert an anti-melanoma effect and promote combination treatment efficacy with anti-PD-1 and anti-cytotoxic T-lymphocyte-associated protein-4 (CTLA4) agents." (PMID 34458265, 2021). "This study suggests a potential utility of this four-gene signature in prognosis, risk assessment, and prediction of anti-CTLA4 response in melanoma patients." (PMID 33753855, 2021). "In relation to this, recent studies demonstrated that the frequency of peripheral blood monocytes in patients with melanoma, was associated with response to anti-CTLA-4 immune checkpoint blockade (ipilimumab) and anti-PD-1 treatment." (PMID 34067757, 2021). "Ipilimumab, a monoclonal antibody that blocks the cytotoxic T lymphocyte-associated antigen 4 (CTLA4) was the first agent approved for the treatment of late-stage melanoma." (PMID 34011268, 2021). "CPI Abs, which mainly target the inhibitory molecules CTLA-4 and PD-1/PD-L1 so far, enhance antitumor T cell activity, especially in tumors with a high mutational load like melanoma or NSCLC." (PMID 33546283, 2021). "In an experimental melanoma, it was determined that anti-CTLA-4 treatment increased the production of TNFα associated with T lymphocytes infiltration, which in turn upregulated Ezh2, silencing tumor cell immunogenicity and antigen presentation." (PMID 33540543, 2021). "Clinical trials of anti-Programmed cell death protein 1 (PD-1) and cytotoxic T-lymphocyte-associated protein (CTLA-4) therapies have demonstrated a clinical benefit with low rates of neurologic adverse events in patients with melanoma brain metastases (MBMs)." (PMID 35096594, 2021). "In this study, we identified a four-gene signature associated with survival and anti-CTLA4 immunotherapeutic responses based on the immune subtype classification of melanoma." (PMID 33753855, 2021). "T-cell reactivity against tumor neoantigens was subsequently demonstrated to underlie clinical responses to immunotherapies, such as CTLA-4 blockade in melanoma and PD-1 blockade in non-small cell lung cancer." (PMID 34201655, 2021). "For example, the clinical responses of PD1 or CTLA4 treated melanoma patients were associated with the intertumoural CD8+ T cell density." (PMID 34367148, 2021). "Our results indicated that patients with MAP2K1/2-mutated melanoma who received anti-CTLA-4 therapy had better OS." (PMID 35069558, 2021). "Previous work identified a high CD4+ TEM cell frequency in blood prior to therapy as a risk marker for PD-1/CTLA-4-related hepatitis in patients with advanced melanoma." (PMID 34868015, 2021). "Of note, in recent years a possible synergy between EZH2 inhibition and blocking the inhibitory checkpoint Cytotoxic T-Lymphocyte Associated Protein 4(CTLA-4) has been suggested, preventing melanoma expansion in resistant patients." (PMID 33467134, 2021). "A lack of IFN-γ pathway genes was found in the nonresponders to anti-CTLA-4 therapy (ipilimumab), and inactivation of the IFN-γ receptor, IFNGR1, caused the resistance to anti-CTLA-4 treatment in mice with melanoma." (PMID 34827646, 2021).